PRDM1 (PR/SET domain 1)
Diseases named in the same sentence as PRDM1 in open-access papers (continued):
Sharing a sentence is not in itself a finding about the gene and the disease.
tumor (continued). "To validate it, we collected experimental datasets and found that the expression level and ssGSEA score of the CD8+ T exhausted specific signature were reduced in CD8+ tumor-infiltrating lymphocytes of Prdm1 cKO mice compared to wild type." (PMID 35903095, 2022). "PRDM1 KO hampers T-cell effector function and tumor control during chronic CAR stimulation despite increases in CAR T-cell proliferative capacity." (PMID 36350986, 2022). "Further, tumoral Prdm1 overexpression upregulates PD-L1 levels, dampening anti-tumor immunity in vivo, and neutralizes the anti-tumor efficacy of Prdm1 overexpression in immune-competent mouse models." (PMID 36509766, 2022). "In T cell-mediated tumor cell-killing assays, PRDM1 overexpressing HCC cells showed increased resistance to activated primary CD45+CD3+ T cells isolated from PBMCs in vitro." (PMID 36509766, 2022). "The results revealed that Prdm1 overexpression in immune-competent mice inhibited tumor proliferation and that Prdm1 knockout contributed to tumor proliferation." (PMID 36509766, 2022). "We expected that Prdm1 overexpression in immune-competent mice would contribute to tumor proliferation and decrease overall survival (OS), and that Prdm1 knockout would display slower tumor proliferation and better OS." (PMID 36509766, 2022). "Since a large proportion of CRC etiologies are derived from stress responses, stress-induced PRDM1 was particularly crucial in tumor cell behavior in the harsh environment." (PMID 33972671, 2021). "The paired t-test revealed significant increase in PRDM1 expression in tumor lesions, compared to the levels in the non-tumor regions (p < 0.05)." (PMID 33972671, 2021). "The clinical survival analysis and xenograft models support the positive regulation of tumor growth by PRDM1 in the CRC." (PMID 33972671, 2021). "Consistent with elevation of PRDM1 expression in tumor tissues of the CRC patients, the protein levels were higher in the gut of APCMin/+ mice than in that of the wild type normal mice." (PMID 33972671, 2021). "While genetic knockdown of PRDM1 expression decreased tumor growth, overexpression of PRDM1 significantly enhanced the tumor size in the xenograft animals." (PMID 33972671, 2021). "The clinical implications of PRDM1 in cancer stemness were also observed in tumor tissues from CRC patients." (PMID 33972671, 2021). "Ribosomal dysfunction-responsive PRDM1 facilitated signaling remodeling for the survival of tumor progenitors, providing compelling evidence for the progression of sporadic CRC." (PMID 33972671, 2021). "Mechanistically, ribosomal stress experience-induced PRDM1 positively regulated IGF receptor-linked pro-survival signals, counteracting the tumor-suppressive action of chemotherapeutics." (PMID 33972671, 2021). "PRDM1/BLIMP1 is a transcriptional repressor expressed by NK cells during development and is a negative regulator of NK function, showing tumor suppressor activity; in NK lymphoma, PRDM1 silencing occurs via deletion of 6q21 and CpG promoter hypermethylation." (PMID 32098335, 2020). "We were not able to extend these experiments beyond 34 days to evaluate tumor relapse, as Prdm1−/−CD4+ T cells have been documented to promote systemic autoimmune toxicities." (PMID 31924474, 2020). "One of the other family members, PRDM1, is a master regulator of B-cell differentiation and acts as a tumor suppressor in DLBCL." (PMID 33287742, 2020). "Patients with different tumor stage and gender didn’t differ in the expression of PRDM1 in tumor samples." (PMID 33384601, 2020). "Cox regression model showed high expression of PRDM1 in tumor samples correlates with poor prognosis in LGG, PAAD, UVM while favorable prognosis in KIRC, SKCM and THCA." (PMID 33384601, 2020). "Generally, PRDM1/BLIMP1 play an immune suppressive role in modulating the local tumor microenvironment." (PMID 33384601, 2020). "For patients with UCEC, the expression level of PRDM1 was lower in tumor samples compared with normal samples." (PMID 33384601, 2020).
tumor (continued). "On average, 30% of Blimp-deficient Trp1 cells still expressed GzmB, potentially explaining the tumor control observed in 50% of Ifngr1−/− recipients treated with Prdm1−/−Trp1 cells." (PMID 31924474, 2020). "To evaluate the role of Blimp-1 on CD4-driven tumor control, we isolated CD4+ TILs from MCA205 tumors and dLNs from αCTLA-4-treated Prdm1fl/fl or Prdm1−/−Cd4cre mice and transferred them to MCA205-bearing Rag1−/− mice." (PMID 31924474, 2020). "The identification of potential tumor suppressor genes, PRDM1 and PTPRK, and pro-survival signaling via MYC and NF-KB are of particular importance as key events in ENKTL pathogenesis." (PMID 29966370, 2018). "This recurrent abnormality, which is observed in 29-52% of ENKTCL arising in immunocompetent individuals, encompasses loci of the FOXO3 and PRDM1 genes, which have been shown to function as tumor suppressors in ENKTCL and subtypes of PTCL." (PMID 27203213, 2016). "We have further characterized this regulatory signature by identifying increased E2f5, Erg1 and Csrnp1, molecules with anti-tumor properties, and Prdm1, whose gene product BLIMP-1 is a negative regulator of interferon (IFN) beta signaling." (PMID 26367386, 2015). "PRDM1 can also promote the apoptosis of tumour cells by specifically suppressing MKI67 and proliferating cell nuclear antigen." (PMID 24438193, 2014). "The inactivation of PRDM1 has been detected in neoplastic NK cells, suggesting that it acts as a tumour suppressor gene." (PMID 24438193, 2014). "In our study, univariate analysis revealed that the frequency of PRDM1-positive expression was significantly higher in early-stage (I/II) than in advanced-stage (III/IV) tumours." (PMID 24438193, 2014). "Prdm1, a transcriptional repressor and effector of Il-6 signaling, was also uniquely up-regulated in disseminated tumor cells, suggesting that active Il-6/Jak/Stat signaling occurs in this population." (PMID 23520493, 2013). "To determine whether the observed impairment in IgA plasma cell differentiation is influenced by tumor anatomical location, we stratified the discovery cohort into left- and right-sided tumors and reevaluated PRDM1 expression and RNA velocity dynamics." (PMID 40667611, 2025). "Notably, PRDM1 has been shown to modulate the tumor microenvironment by dampening immune responses, and its deletion has been associated with enhanced antitumor T cell activity." (PMID 40936897, 2025). "Further research may provide deeper insight into the role of PRDM1 in the anti-tumor function of human NK cells, enabling a more direct investigation of its application in cancer therapies." (PMID 39133873, 2024). "Prdm1 safeguards group 1 ILCs from exhaustion-like phenotypes in the tumor microenvironment." (PMID 39133873, 2024). "Therefore, we initiated an in vivo tumor model to further investigate the impact of Prdm1 on NK cell anti-tumor capability." (PMID 39133873, 2024). "PRDM1/BLIMP-1, a transcriptional repressor, plays a crucial role in regulating cell fate decisions during embryonic development and sustaining tissue homeostasis, while also functioning as a tumor suppressor." (PMID 39562537, 2024). "Prdm1 is required for group 1 ILCs to control tumor metastasis." (PMID 39133873, 2024). "The significant increase in this cell population following Prdm1 knockout in NK cells may potentially be one of the reasons why Prdm1 cko mice lose their tumor-killing capacity." (PMID 39133873, 2024). "They detected an overexpression of PRDM1 protein in all analyzed tumors within the epithelial component and palatine tonsil tissues, but no expression was observed in the lymphoid germinal centers or tissues surrounding the tumor." (PMID 39684268, 2024).
tumor (continued). "Among the genomic biomarkers able to discriminate transformed tumours (hEMT, MES) from the epithelial state, we identified genes that have been previously linked with cell migration, invasion and EMT, such as RB1, VHL, ERBB2, ARHGAP26, PRDM1, APC." (PMID 36774358, 2023). "PRDM1 single KO moderately enhanced tumor control and survival." (PMID 36350986, 2022). "Similarly, the Prdm1 knockout group showed similar tumor proliferation and survival time comparable to the sgCtrl group." (PMID 36509766, 2022). "The marginally enhanced tumor control observed with this single modification may be attributed to the large increase in the number of PRDM1 KO CAR T-cells in vivo, despite upregulation of exhaustion pathways and concomitantly diminished effector function." (PMID 36350986, 2022). "However, co-treatment with Prdm1 knockout and PD-1 mAb had a limited effect on tumor growth and survival time compared with Prdm1 knockout alone." (PMID 36509766, 2022). "Hence, to show an unbiased and comprehensive perspective of the tumor microenvironment affected by PRDM1 expression, we performed scRNA-seq using HCC biopsies before PD-1 mAb-based therapies." (PMID 36509766, 2022). "Regulation of the cell death pathway was also significantly enriched, indicating that PRDM1 might suppress the proliferation ability of HCC cell lines by mediating tumor cell death." (PMID 36509766, 2022). "In the negative coexpression genes, GO and KEGG analyses suggest that PRDM1 may alter tumor metabolism." (PMID 35607327, 2022). "The Prdm1 and sgPrdm1 groups and their corresponding controls showed comparable tumor sizes." (PMID 36509766, 2022). "However, after multiple tumor cell stimulations, PRDM1 KO CAR T-cells exhibited dramatically reduced effector cytokine secretion." (PMID 36350986, 2022). "Given that Blimp1, encoded by PRDM1, is a negative regulator of NK cell function it can be hypothesized that tumor-associated Tregs might also induce NK cell suppression via this mechanism." (PMID 35414042, 2022). "In addition to the tumor growth-promoting actions of PRDM1, we further assessed its contribution to cancer cell survival in a harsh condition, such as anticancer stress." (PMID 33972671, 2021). "Moreover, PRDM1-mediated alteration of cancer cell signal was assessed in tissues of the xenograft tumor model." (PMID 33972671, 2021). "These tumor growth-promoting actions of PRDM1 were also verified in an ectopic xenograft model." (PMID 33972671, 2021). "Collectively, our results allowed the decipherment of a functional axis whereby KPNA2 assisted the nuclear import of CBX8 to activate downstream effectors by recruiting BCOR to the promoter region of PRDM1, thus highlighting the tumor-promoting properties of KPNA2 in BCa." (PMID 33731128, 2021). "Further investigation of other transcripts in the pan-drug signature reveal that most have a known tumor suppressive function but others such as PRDM1, SESN1/2 may play a complicated or multiplex role in CRC and other cancers." (PMID 34611476, 2021). "Based on these results, it was thus assumed that non-canonical Wnt signaling-linked stemness is involved in PRDM1-linked tumor cell survival." (PMID 33972671, 2021). "The tumor-promoting effects of KPNA2 via the PRDM1/c-FOS pathway were also validated in vivo." (PMID 33731128, 2021). "Experimentally, adenocarcinoma-derived PRDM1 was positively involved in the tumor mass increase." (PMID 33972671, 2021). "On the hand, there are also reported showed PRDM1 in cancer cell plays a tumor suppressive role." (PMID 33384601, 2020). "SIRT1, Ki-67, and PRDM1 mRNA levels were also elevated in CRC tumor tissues; these markers could contribute to CRC by promoting tumorigenesis, and inducing T cell exhaustion and functional impairment via indirect mechanisms." (PMID 32393998, 2020).
tumor (continued). "For instance, array comparative genomic hybridization and gene expression profiling in extranodal NK/T-cell lymphoma (EN-NK/T) revealed that the most frequently deleted chromosomal region 6q21-6q25, induced a downregulation of several tumor-suppressor genes including PRDM1." (PMID 32290321, 2020). "On the other hand, engineering tumor specific T cells by down regulating the expression of PRDM1 could also be a promising strategy to enhance the efficacy of adoptive immunotherapy." (PMID 33384601, 2020). "Indeed, using a combination of genomic and functional analyses, several independent groups have produced converging evidence supporting a tumor suppressor function of PRDM1/Blimp1 in ENKTL." (PMID 30935402, 2019). "Copy number analyses have highlighted potential tumor suppressor genes such as PR Domain Zinc Finger Protein 1 (PRDM1) and protein tyrosine phosphatase kappa (PTPRK) while next generation sequencing studies have identified recurrently mutated genes in pro-survival and anti-apoptotic pathways." (PMID 29966370, 2018). "They identified several candidate tumor-suppressor genes that were down-regulated in these regions and their subsequent investigations suggested that two of these suppressor genes, PRDM1 and FOXO3, were considered playing an important role in the pathogenesis of NK-cell neoplasms." (PMID 26141723, 2015). "Our findings reveal that the downregulation of the tumour suppressor PRDM1 in EN-NK/T-NT samples is mediated by miR-223 and that PRDM1-positive staining might have prognostic value for evaluating the clinical outcome of EN-NK/T-NT patients." (PMID 24438193, 2014). "The expression of PRDM1 protein in 61 primary EN-NK/T-NT tumour specimens was assessed by IHC." (PMID 24438193, 2014). "PRDM1 positive staining was observed in the nuclei of tumour cells." (PMID 24438193, 2014). "PRDM1, also known as B lymphocyte-induced maturation protein 1 (BLIMP1), has been shown to impair the stemness and growth activity of CAR T cells, as indicated by TCF7, which is closely associated with the exhaustion phenotypes of CAR T cells in anti-tumor therapies." (PMID 39678513, 2024). "Thus, T cell-mediated immune evasion impedes the anti-tumor effect of PRDM1 overexpression." (PMID 36509766, 2022). "Thus, above results confirmed that Prdm1 may promote tumor immune evasion by driving PD-L1 upregulation and neutralizing the anti-tumor efficacy of Prdm1 overexpression." (PMID 36509766, 2022). "Therefore, we focused on the anti-tumor immunity of PRDM1 through PD-L1 regulation." (PMID 36509766, 2022). "Although the ranking order may vary, the majority of the top-ranked TEff/EM regulons such as Rora, Fosl2, Creb3, Maf, Prdm1, Nfil3, and Nfkb1 were also identified as top-ranked regulons for active TRMs in the tumor and distant mammary mucosa." (PMID 33979626, 2021). "Additionally, the involvement of PRDM1 in CRC stemness was tested in tumor spheroids." (PMID 33972671, 2021). "Considering T-bet does not appear regulate GzmB expression and the high levels of Prdm1 mRNA observed in CD4+ Th-ctx cells post-αCTLA-4 treatment, we explored whether Blimp-1 contributed to the acquisition of a cytotoxic phenotype by CD4eff T cells and to the overall anti-tumor activity of αCTLA-4." (PMID 31924474, 2020). "Therefore, the distinct prognostic value of high PRDM1 expression across different cancers may result from its synthetic effect of immune suppressive activity and tumor suppressive activity in each cancer type." (PMID 33384601, 2020).
tumor (continued). "Additionally, since some PRDMs (e.g., PRDM1, 9, 11, 14, 16) are able to orchestrate the differentiation of B and T lymphocytes, their involvement in the control of a more incisive immune response to neoplasia cannot be excluded." (PMID 32290321, 2020). "Knocking out PGC specification inducers (ACVR1, SMAD5, PRDM1, or SOX17) or fate-maintaining genes (NANOG or DDX4) suppressed both SPLC and tumor initiation." (PMID 42291258, 2026). "Disruption of PRDM1 using CRISPR-Cas9 promoted the expansion of less-differentiated memory CAR-T cells in vivo and enhanced T-cell persistence in multiple tumor models." (PMID 41181132, 2025). "Two studies have shown that CRIPSR/Cas9 KO of PRDM1 in CAR-T cells results in improved persistence and overall enhanced tumour control in preclinical models of haematological and solid cancers including leukaemia, melanoma and prostate cancer." (PMID 39399500, 2024). "The regulon specificity score (RSS) highlighted unique regulons across the three studied regions, with MITF(+), PRDM1(+), MAX(+), TFEC(+), and BHLHE41(+) emerging as the most specific regulons within the tumor core." (PMID 38938448, 2024). "TF factor motif analysis within H3K27ac peaks revealed 29 MG63-specific TF binding sites, including those for EOMES, PRDM1, EPAS1 (HIF2A), E2F6, and MYC/MAX, which reflect known early development, tumor-initiation, and stemness factors (Worksheet 1)." (PMID 37228489, 2023). "RB1, PRDM1, and TP63 expression was significantly downregulated in tumor samples with distant metastasis compared to tumor samples without metastasis, based on both TCGA and GSE30219 datasets." (PMID 38057344, 2023). "The tumor-suppressive function of FOXO3 and PRDM1 in NK cell neoplasms was proven by genomic and functional analyses." (PMID 35054466, 2022). "Knocking out PRDM1, which suppressed PPAR-γ co-activator (PGC) 1α, which upregulates antioxidant enzymes, increased mitochondrial mass and IFNγ production of tumor-infiltrating T cells exposed to chronic hypoxic stimulation ex vivo." (PMID 35414042, 2022). "Other 6q15 genes with potential tumor suppressive functions for example include EEF1A1, ZNF292, SNORD50A, PRDM1, CCNC, FOXO3, WISP3, and FRK." (PMID 34625909, 2022). "Here, we found that PRDM1-overexpressing HCC cells upregulated PD-L1 expression and inhibited T cell-mediated anti-tumor immunity, thus dampening its role as a tumor growth suppressor in immunocompetent mice." (PMID 36509766, 2022). "PRDM1 upregulation impaired the CD8+ T cell activation (CD8+GZMB+ T cells) and T cell-mediated tumor cell killing activity (CD8+TNFα+ T cells) in the co-culture, whereas PRDM1 knockout had contrasting effects." (PMID 36509766, 2022). "Of these, five candidate tumor-suppressor genes, including FOXO3, HACE1, PRDM1, ATG5, and AIM1, were identified in the minimal region in del 6q21." (PMID 35054466, 2022). "In an in vivo “stress test” in which tumor burden is escalated to reveal CAR T-cell functional limits, PRDM1 KO CAR T-cells showed comparable antitumor activity to AAVS1 KO CAR T-cells." (PMID 36350986, 2022). "The downregulation of oncogenes such as IRF-4, XBP-1, PRDM1/BLIMP-1 and c-MYC, as well as the upregulation of tumor-suppressive microRNAs like miR-125a-3p and miR-320c, have also been shown." (PMID 34439223, 2021). "Taken all, ribosomal dysfunction-responsive PRDM1-IGF signaling contributed to cancer cell stemness and subsequent tumor cell survival from anticancer actions via preferential regulation of non-canonical Wnt-linked pathways." (PMID 33972671, 2021). "Furthermore, PRDM1 overexpression could counteract the pro-tumor effects of KPNA2." (PMID 33731128, 2021).